LSS (lanosterol synthase)
Description:
Key enzyme in the cholesterol biosynthesis pathway. Catalyzes the cyclization of (S)-2,3 oxidosqualene to lanosterol, a reaction that forms the sterol nucleus. Through the production of lanosterol may regulate lens protein aggregation and increase transparency.
Synonyms: OSC; APMR4; CTRCT44; HYPT14
Tractability: Small molecule: a structure with a bound ligand is known; a high-quality ligand is known; it has a high-quality binding pocket; it belongs to a druggable protein family. Antibody: UniProt places it where antibodies can reach, with high confidence. PROTAC: ubiquitination databases record sites on it; its protein half-life has been measured; a small molecule that binds it is known.
Target class: Isomerase; Enzyme
Gene: Protein-coding gene on chromosome 21 (46,188,141 to 46,228,840, reverse strand). Ensembl gene ENSG00000160285.
Subcellular location: Endoplasmic reticulum membrane
Pathways (Reactome):
Metabolism: Activation of gene expression by SREBF (SREBP); Lanosterol biosynthesis
Gene Ontology:
Molecular function: lanosterol synthase activity; protein binding; intramolecular transferase activity
Biological process: cholesterol biosynthetic process; regulation of protein stability; steroid biosynthetic process; triterpenoid biosynthetic process; zymosterol biosynthetic process
Cellular component: endoplasmic reticulum membrane; lipid droplet; membrane; cytoplasmic side of endoplasmic reticulum membrane
Genetic constraint (gnomAD): Loss-of-function variants: 90 observed, 102.11 expected, observed/expected ratio (o/e) 0.88, 90% interval 0.74 to 1.05. The upper end of that interval is the gene's LOEUF score, 1.05, which puts it in group 4 of 6, group 1 being the genes least tolerant of losing a copy. Missense variants: 927 observed, 976.33 expected, observed/expected ratio (o/e) 0.95, 90% interval 0.9 to 1. Synonymous variants: 433 observed, 400.46 expected, observed/expected ratio (o/e) 1.08, 90% interval 1 to 1.17.
Homologues: Orthologues: chimpanzee LSS (99% identical), macaque LSS (93% identical), dog LSS (86% identical), mouse Lss (86% identical), guinea pig LSS (86% identical), rat Lss (84% identical), rabbit LSS (82% identical), pig LSS (79% identical), zebrafish lss (75% identical), tropical clawed frog lss (75% identical).
Diseases named in the same sentence as LSS in open-access papers:
LSS is named in the same sentence as 60 diseases in open-access papers, as found by Europe PMC text mining. Sharing a sentence is not in itself a finding about the gene and the disease. The quoted sentences say what the papers report.
cataract (13 papers, 2007 to 2025). Partial or complete opacity of the crystalline lens of one or both eyes that decreases visual acuity and eventually results in blindness. "LSS mutations have been associated with cataracts (OMIM 600909), hypotrichosis (OMIM 618275) in affected children, and a phenotype referred to as alopecia-intellectual disability syndrome-4 (OMIM 618840)." (PMID 38672427, 2024). "It has been reported that the mutation of the LSS gene can cause cholesterol-deficiency-associated cataracts, kidney injury and alopecia, suggesting the importance of LSS in steroid metabolism homeostasis." (PMID 36766250, 2023). "Mutation analyses in mice and rats confirmed that LSS was a causative gene for alopecia and cataracts." (PMID 36685177, 2022). "Our mouse studies underscored that hypotrichosis and cataracts are caused by LSS enzymatic dysfunctions in each tissue." (PMID 32101538, 2020). "Our mouse studies confirmed that LSS deficiency causes hypotrichosis and cataracts due to loss-of-function mutations in LSS in each tissue." (PMID 32101538, 2020). "Our results confirmed that hypotrichosis and cataracts, the core symptoms in patients with biallelic LSS mutations, are caused by LSS enzymatic deficiency in each tissue, not by circulating abnormal metabolites in the blood." (PMID 32101538, 2020). "Similarly, patients with different LSS mutations always present different symptoms, such as alopecia, alopecia-mental retardation syndrome, or cataracts." (PMID 36685177, 2022). "LSS mutations have been identified in patients with cataracts or hypotrichosis." (PMID 36685177, 2022). "Moreover, the reason why each patient with biallelic LSS mutations shows different combinations of phenotypes, such as hypotrichosis and/or cataracts, is also unknown." (PMID 32101538, 2020). "Our previous studies have shown that lanosterol synthase (LSS) has the ability to reverse the aggregation of lens proteins and prevent cataracts." (PMID 39922821, 2025). "The heterozygous c.1120G>A/p.Asp374Asn of the LSS was identified only in a patient with a history of cataracts (Case ju6)." (PMID 38785568, 2024). "LSS converts (S)-2,3-epoxysqualene to lanosterol in the cholesterol biosynthesis pathway, and lanosterol reverses protein aggregation in cataracts." (PMID 34926465, 2021). "LSS gene variants have been associated with various conditions such as congenital hypotrichosis and cataracts, but the genotype-phenotype relationship remains not well understood." (PMID 40364812, 2025). "Thus, our study provides direct evidence that LSS plays an essential role in lens development, which will contribute to a better understanding of LSS functions in cataractogenesis and develop therapeutic approaches to cataracts." (PMID 34926465, 2021). "We identified two patients with novel biallelic LSS mutations who exhibited congenital hypotrichosis and midline anomalies but did not have cataracts." (PMID 32101538, 2020). "Here, we report two siblings with novel biallelic LSS mutations who presented congenital hypotrichosis, midline anomalies, such as cleft palate and agenesis of the corpus callosum, and no cataracts." (PMID 32101538, 2020). "On the other hand, SCR-C carries a specific combination of hypomorphic mutations of lanosterol synthase and FDFT1 (farnesyl-diphosphate-farnesyl-transferase-1) genes, and the mutation of the lanosterol synthase gene results in decreased cholesterol levels in the lens, causing cataracts." (PMID 32033321, 2020).
congenital cataracts (13 papers, 2018 to 2025). "In humans, mutations in the LSS gene can lead to congenital cataracts and alopecia, while its effects in animals are typically associated with fat deposition." (PMID 39765715, 2024). "Defects in lanosterol synthase (LSS), which synthesises lanosterol, have also been found to be associated with congenital cataracts in humans." (PMID 38440190, 2024). "Biallelic mutations in LSS have been reported in families with congenital cataracts and, very recently, have been reported in cases of hypotrichosis." (PMID 32101538, 2020). "In humans, hypomorphic mutations in LSS result in congenital cataracts, hypotrichosis simplex and alopecia with mental retardation syndrome." (PMID 32430393, 2020). "LSS gene variants are linked to a variety of disorders, such as congenital cataracts, alopecia-intellectual disability syndrome, hypotrichosis simplex, and mutilating palmoplantar keratoderma, that have varying dermatological, ocular, and neurological symptoms." (PMID 40364812, 2025). "LSS, which encodes lanosterol synthase, is a causal gene for congenital cataracts." (PMID 34926465, 2021). "Biallelic mutations in LSS were first reported in families with congenital cataracts." (PMID 32101538, 2020). "Abnormal mutational expression of the LSS gene caused congenital cataracts (OMIM# 616,509), APMR4 (OMIM#618,840), and autosomal recessive hypotrichosis (OMIM# 618,275)." (PMID 36251212, 2022). "LSS encodes lanosterol synthase, an enzyme in the cholesterol biosynthesis pathway, and biallelic mutations in LSS have been reported in families with congenital cataracts and hypotrichosis." (PMID 32101538, 2020). "LSS variants have also been shown to cause hypotrichosis with or without intellectual disability, congenital cataracts, or cognitive impairment." (PMID 40364812, 2025).
alopecia (9 papers, 2020 to 2025). Hair loss usually from the scalp. "According to the ACMG standards, 75% of these variants were variants of uncertain significance (Class 3); two pathogenic (Class 5) variants were identified in TCHH and LSS, genes associated with uncombable hair syndrome, and macrocephaly, alopecia, cutis laxa, and scoliosis, respectively." (PMID 38791074, 2024). "This hypothesis is supported by the evidence that inducible epidermis-specific deletion of LSS causes alopecia." (PMID 36685177, 2022). "Some LSS mutations cause alopecia alone and others cause alopecia with intellectual disability; this clinical heterogeneity remains unclear." (PMID 36251212, 2022). "For example, the CCDC41 gene variants would be present in nephronophthisis; LSS gene variants can result in alopecia; LTBP3 gene variants are characterized by hypoplastic amelogenesis imperfecta; NTRK1 gene variants have been found to cause congenital insensitivity to pain." (PMID 35911831, 2022). "In conclusion, the hypotrichosis simplex reported here could be an autosomal recessive disease in this family, and the mutation on LSS might reduce LSS enzyme activity, thus leading to alopecia." (PMID 36685177, 2022). "Bi-allelic mutations of LSS were found to lead to alopecia in all cases reported earlier." (PMID 36685177, 2022). "We studied one patient with LSS-related APMR4 who presented with severe intellectual disability, alopecia, early-onset epilepsy and developmental delay." (PMID 38800572, 2024).
hypotrichosis (8 papers, 2020 to 2025). A congenital condition, usually due to genetic aberrations, that is characterized by a lack of hair growth on the head and/or body. "It is interesting that four LSS mutations causing CC are located toward the C terminus, while five LSS mutation-causing autosomal-recessive hair loss disorders (hypotrichosis) are located toward the N terminus." (PMID 34926465, 2021). "We showed that LSS metabolic inhibition in patients with biallelic LSS mutations and congenital hypotrichosis in vivo by measuring metabolites of the LSS enzyme in the forehead sebum, which would be good biomarkers for the diagnosis of LSS deficiency." (PMID 32101538, 2020). "Meanwhile, the proband’s mother was asymptomatic, raising the question of whether a mutation in LSS has a dose effect on hypotrichosis simplex, which is worth investigating." (PMID 36685177, 2022). "Hypotrichosis-14 is a rare form of autosomal recessive nonsyndromic hypotrichosis marked by sparse or absent lanugo-like hair on the scalp, as well as reduced or missing eyebrows, eyelashes, and body hair due to mutation of LSS gene." (PMID 39845463, 2025).
hypotrichosis simplex (5 papers, 2020 to 2024). Hypotrichosis simplex (HS) or hereditary hypotrichosis simplex (HHS) is characterized by reduced pilosity over the scalp and body (with sparse, thin, and short hair) in the absence of other anomalies. "This study reports new mutations in the LSS gene, providing valuable insights into the association between hypotrichosis simplex and the LSS gene, contributing to the understanding of the genetic basis of hypotrichosis simplex." (PMID 39152648, 2024). "This study aims to find mutations in LSS from a Chinese family, among which a 21-year-old male patient and his 9-year-old sister were affected by hypotrichosis simplex." (PMID 36685177, 2022). "More recently, several studies have identified mutations in the lanosterol synthase encoding gene LSS from patients affected by hypotrichosis simplex, suggesting LSS could also be associated with the disease." (PMID 36685177, 2022). "This study aimed to find new mutations in LSS related to hypotrichosis simplex." (PMID 36685177, 2022). "In addition, different LSS mutations have been found in patients affected by hypotrichosis simplex previously." (PMID 36685177, 2022). "Previous studies have reported many casual genes associated with heredity hypotrichosis simplex such as LSS, CDSN, and APCDD1, while other studies highlighted that CDH3 variants cause hypotrichosis simplex with juvenile macular dystrophy (HJMD; OMIM #601553) that is manifested later in life." (PMID 35962736, 2022).
Alopecia intellectual disability syndromes 4 (3 papers, 2022 to 2024). "Alopecia intellectual disability syndromes 4 (APMR4) caused by Lanosterol synthase (LSS) gene variants is a very rare autosomal recessive neuroectodermal syndrome." (PMID 38800572, 2024). "Alopecia intellectual disability syndromes 4 (APMR4) is a very rare autosomal recessive condition caused by a mutation in the LSS gene present on chromosome 21." (PMID 36251212, 2022).
Intellectual disability (3 papers, 2022 to 2025). "Additionally, certain LSS mutations may directly affect the function of neuronal cells, leading to neurological disorders such as intellectual disabilities." (PMID 38800572, 2024).
pancreatic cancer (3 papers, 2015 to 2023). "In metastatic mouse models of colorectal and pancreatic cancer, lanosterol synthase (LSS) promotes tumor neovascularization and metastasis." (PMID 37089950, 2023). "Targeting lanosterol synthase (LSS) by R048–8071 represses the phosphorylation of AKT and inhibits the growth and metastasis of both pancreatic cancer and CRC." (PMID 38023258, 2023).
phospholipidosis (3 papers, 2012 to 2023). "Amiodarone induced phospholipidosis may also be explained by an indirect mechanism of upregulation of the fatty acid biosynthesis-related gene SCD, causing enhanced synthesis of phospholipids, and overexpression of lanosterol synthase (LSS), associated with cholesterol synthesis." (PMID 26273591, 2015). "In particular, the upregulation of the genes MSMO1, IDI1, LSS, and HMGCR suggested enhanced synthesis of cholesterol, and the upregulation of FASN suggested an increased synthesis of fatty acids that may in turn induce phospholipidosis." (PMID 37745076, 2023).
alopecia-mental retardation syndrome (2 papers, 2021 to 2022). "In addition, mutations of LSS can cause alopecia-mental retardation syndrome (APMR), which is a rare autosomal recessive neuro-dermal disorder." (PMID 34926465, 2021).
atherosclerosis (2 papers, 2025). A disease characterized by the build-up of fatty material and calcium deposition in the arterial wall resulting in partial or complete occlusion of the arterial lumen. "Due to the enzyme's important role in CHOL biosynthesis, interest has grown in LSS inhibitors as drugs to lower blood CHOL, treat atherosclerosis and inhibit tumor growth recently." (PMID 40007440, 2025). "The expression of other key atherosclerosis-related enzymes, including cytochrome P450 8B1 (CYP8B1) and lanosterol synthase (LSS), was downregulated, whereas the expression of cyclooxygenase 2 (COX-2) and aldo–keto reductase family 1 member C3 (AKR1C3) was induced by PFOS and PFOA." (PMID 40728694, 2025).
breast carcinoma (2 papers, 2020 to 2025). "Inhibiting CHOL biosynthesis using lanosterol synthase (LSS) inhibitor RO48‐8071 (RO) significantly inhibited hormone‐dependent and castration‐resistant PCa cells in vitro and PCa tumor growth in in vivo tumor xenograft mice models and breast cancer." (PMID 40007440, 2025).
fatty liver disease (2 papers, 2023 to 2026). A reversible condition wherein large vacuoles of triglyceride fat accumulate in liver cells via the process of steatosis. "LSS loss of function alleviates liver injury and hepatic steatosis via reducing fatty deposition and triglyceride accumulation in hepatocytes." (PMID 41845094, 2026).
CHILD syndrome (1 paper, 2020). CHILD syndrome (Congenital Hemidysplasia with Ichthyosiform nevus and Limb Defects, CS) is an X-linked dominant genodermatosis characterized by unilateral inflammatory and scaling skin lesions with ipsilateral visceral and limb anomalies. "Local treatment in LSS deficiency might alleviate symptoms; patients with CHILD syndrome, a deficiency of downstream intermediates of LSS, was successfully treated by topical application of statin or cholesterol plus statin." (PMID 32101538, 2020).
colorectal cancer (1 paper, 2023). A primary or metastatic malignant neoplasm that affects the colon or rectum. "The results reveal that most of the identified essential genes were compatible with the colorectal cancer cell lines obtained from DepMap and that these genes, with the exception of EBP, LSS, and SLC7A6, could generate a high level of cell death when knocked out." (PMID 37205704, 2023).
COVID-19 (1 paper, 2024). A disease caused by infection with severe acute respiratory syndrome coronavirus 2. "In sum, this study identifies seven lipophagy-related genes (ACADVL, HYOU1, DAP, AUP1, PRXAB2, LSS, and PLIN2) as biomarkers and potential therapeutic targets for COVID-19." (PMID 38932215, 2024). "Seven lipophagy-related genes, including ACADVL, HYOU1, DAP, AUP1, PRXAB2, LSS, and PLIN2, were used as biomarkers and drug targets for COVID-19." (PMID 38932215, 2024). "In the validation set (GSE190496), we observed a significant increase in the gene expression levels of LSS, HYOU1, ACADVL, PRKAB2, PLIN2, AUP1, and DAP in the COVID-19 group compared to the control group." (PMID 38932215, 2024). "The lipophagy-related genes ACADVL, HYOU1, DAP, AUP1, PRXAB2, LSS, and PLIN2 can be used as biomarkers and drug targets for COVID-19." (PMID 38932215, 2024).
endometrial cancer (1 paper, 2025). Primary or metastatic malignant neoplasm involving the endometrium (mucous membrane that lines the endometrial cavity). "To explore the role of LSS in endometrial cancer (EC), we first analyzed its expression in the GEO dataset GSE39099." (PMID 39922821, 2025). "This study demonstrates that LSS is a key regulator of cholesterol metabolism, driving endometrial cancer (EC) cell growth and tumorigenesis." (PMID 39922821, 2025).
glioma (1 paper, 2017). A benign or malignant brain and spinal cord tumor that arises from glial cells (astrocytes, oligodendrocytes, ependymal cells). "Finally, we found that glioma cells, but not normal astrocytes, are sensitive to shutting down cholesterol synthesis through pharmacological inhibition of lanosterol synthase or CYP51A1 in a density-dependent manner." (PMID 28118603, 2017).
holoprosencephaly (1 paper, 2020). Holoprosencephaly (HPE) is a complex brain malformation resulting from incomplete cleavage of the prosencephalon, occurring between the 18th and 28th day of gestation, and affecting both the forebrain and face, which results in neurological manifestations and facial anomalies of variable severity. "Although the association of LSS mutations and holoprosencephaly was not proven by pedigree analysis in a previous study, some patients with LSS mutations, including our patients, have midline anomalies or growth failure, which are observed in diseases of cholesterol metabolism or SHH signaling." (PMID 32101538, 2020).
Hypertension (1 paper, 2023). The presence of chronic increased pressure in the systemic arterial system. "Recently, a polymorphism affecting the activity of lanosterol synthase has been associated with an increased risk of hypertension in adolescents." (PMID 37628669, 2023).
metastatic disease (1 paper, 2022). "Finally, the use of inhibitors targeting post-squalenic enzymes of the MVA pathway to limit metastatic disease, such as lanosterol synthase (LSS) or NAD(P)H steroid dehydrogenase-like (NSDHL) shows encouraging results." (PMID 35945203, 2022).
psoriasis (1 paper, 2023). An autoimmune condition characterized by red, well-delineated plaques with silvery scales that are usually on the extensor surfaces and scalp. "Excessive proliferation and defective differentiation of KCs are typical characteristics of psoriasis, and the mutations in the lanosterol synthase (LSS) gene have been proven to induce over-proliferation and differentiation disorders of KCs." (PMID 37234169, 2023).
Q fever (1 paper, 2022). A bacterial infection caused by Coxiella burnetii.